HOXA3 (homeobox A3)
Description:
Sequence-specific transcription factor which is part of a developmental regulatory system that provides cells with specific positional identities on the anterior-posterior axis.
Synonyms: HOX1E; HOX1
Tractability: No criterion of Open Targets' tractability assessment is met for any kind of drug.
Gene: Protein-coding gene on chromosome 7 (27,106,184 to 27,152,610, reverse strand). Ensembl gene ENSG00000105997.
Subcellular location: Nucleus
Subcellular location (Human Protein Atlas): Nucleoplasm
Pathways (Reactome):
Developmental Biology: Activation of anterior HOX genes in hindbrain development during early embryogenesis
Gene Ontology:
Molecular function: protein binding; DNA-binding transcription factor activity, RNA polymerase II-specific; RNA polymerase II cis-regulatory region sequence-specific DNA binding; DNA binding; DNA-binding transcription factor activity; HMG box domain binding
Biological process: angiogenesis; anterior/posterior pattern specification; embryonic skeletal system morphogenesis; regulation of transcription by RNA polymerase II; regulation of DNA-templated transcription
Cellular component: nucleoplasm; chromatin; nucleus
Genetic constraint (gnomAD): Loss-of-function variants: 8 observed, 26.54 expected, observed/expected ratio (o/e) 0.3, 90% interval 0.18 to 0.54. The upper end of that interval is the gene's LOEUF score, 0.54, which puts it in group 2 of 6, group 1 being the genes least tolerant of losing a copy. Missense variants: 621 observed, 573.57 expected, observed/expected ratio (o/e) 1.08, 90% interval 1.01 to 1.16. Synonymous variants: 307 observed, 260.95 expected, observed/expected ratio (o/e) 1.18, 90% interval 1.07 to 1.29.
Homologues: Orthologues: chimpanzee HOXA3 (99% identical), macaque HOXA3 (98% identical), dog HOXA3 (95% identical), pig HOXA3 (95% identical), mouse Hoxa3 (94% identical), guinea pig HOXA3 (93% identical), rat Hoxa3 (93% identical), rabbit HOXA3 (90% identical), tropical clawed frog hoxa3 (66% identical), zebrafish hoxa3a (56% identical), zebrafish hoxc3a (18% identical). Paralogues in human: HOXB3 (52% identical), HOXD3 (50% identical), HOXB2 (22% identical), PDX1 (21% identical), HOXA2 (21% identical), HOXD4 (18% identical), HOXB4 (17% identical), HOXA4 (16% identical), HOXA1 (16% identical), GSX2 (16% identical), HOXB1 (16% identical), HOXC4 (15% identical), and 30 more.
Diseases named in the same sentence as HOXA3 in open-access papers:
HOXA3 is named in the same sentence as 39 diseases in open-access papers, as found by Europe PMC text mining. Sharing a sentence is not in itself a finding about the gene and the disease. The quoted sentences say what the papers report.
breast carcinoma (6 papers, 2019 to 2025). "Another study showed that circ_0008945 was increased in breast cancer(BC) and promoted BC cell proliferation, migration and invasion by sponging miR-1271 and miR-338-3p to release HOXA3." (PMID 37161408, 2023). "A recent study found that miR-338-3p targeted and inhibited HOXA3 in breast cancer." (PMID 33240592, 2020). "Although little is known about HOXA4 in breast cancer currently, the co-occurrence of HOXA3, A4, A5 and A7 in these rules identified an intimate expression relationship between HOXA4 and the other three HOXA genes, suggesting its potential role in carcinogenesis." (PMID 31703610, 2019).
glioma (6 papers, 2020 to 2025). A benign or malignant brain and spinal cord tumor that arises from glial cells (astrocytes, oligodendrocytes, ependymal cells). "Then, via LASSO and Cox regression analyses, immune signatures were constructed using HLA-DQA2, HOXA3, and SAA2, and IDH1mt-glioma patients were divided into high-risk and low-risk groups." (PMID 36159801, 2022). "In conclusion, an immune signature constructed using HLA-DQA2, HOXA3, and SAA2 exhibited significant and specific prognostic value for IDH1mt glioma, while the high-risk group classified by the signature had a high benefit from ICB." (PMID 36159801, 2022). "In gliomas, HOXA3, A7, A9, and A10 are methylation targets mainly in high-grade tumors, and their role as potential biomarkers has been proposed to clinically distinguish among patient subgroups." (PMID 32635388, 2020). "For HOXA3, differential methylation profiles were found in glioma, lung and penile carcinomas, leading to its consideration as part of the methylome signature associated with these diseases." (PMID 32635388, 2020). "Jiang’s study also identified the prognostic roles of HOXA3 in low-grade glioma." (PMID 37351805, 2023). "Besides, the methylation of HOXA3 contributed to a longer survival time in high-grade glioma patients." (PMID 37351805, 2023). "Upregulated HOXA3 was observed in series of cancers, including glioma." (PMID 36159801, 2022). "Furthermore, ROC analysis was performed to determine the diagnostic value of HLA-DQA2, HOXA3, and SAA2 in the survival of IDH1mt-glioma patients, and all showed remarkable diagnostic value (AUC = 0.832, 0.896, and 0.857)." (PMID 36159801, 2022). "We then performed a multivariate Cox regression analysis, and the immune signature constructed using HLA-DQA2, HOXA3, and SAA2 was found to act as an independent prognostic factor for glioma patients with IDH1mt, with an HR of 1.203." (PMID 36159801, 2022). "A multivariate Cox analysis also indicated that HLA-DQA2, HOXA3, and SAA2 were independent predictors of survival in glioma patients with IDH1mt." (PMID 36159801, 2022). "IHC was performed to detect the expression of HLA-DQA2, HOXA3, and SAA2 in glioma tissues, and high expression of HLA-DQA2, HOXA3, and SAA2 was observed in glioma tissues in the short-term group compared with that in the long-term group." (PMID 36159801, 2022). "In this study, we focused on the IDH1mt subtype glioma and found that the risk model constructed using HLA-DQA2, HOXA3, and SAA2 showed remarkable prognostic value for IDH1mt glioma in both TCGA and CGGA cohorts but not for wtIDH1-glioma." (PMID 36159801, 2022). "Therefore, the gene expression information of HLA-DQA2, HOXA3, and SAA2 and the survival information of glioma patients with IDH1mt in TCGA were imported into R software to construct a risk model." (PMID 36159801, 2022). "Furthermore, antisense RNA of HOXA3 and HOXA11 have also shown prognostic values in glioma." (PMID 37351805, 2023). "Among the seven key genes (HOXD11, HOXC9, HOXC6, HOXA3, FBXO39, OTP, and HMGA2) consistently detectable in both normal astrocyte cell lines (SVG-P12) and glioma cell lines (U87, U251, LN229), tumor cell lines exhibited significantly upregulated expression compared to normal cell lines." (PMID 41049291, 2025).
diabetes (5 papers, 2016 to 2022). "A possible mechanism by which Hoxa3 may limit inflammation was investigated in that experiment by modulating the p65 subunit of NF-ⱪB and investigating its association with the aberrant inflammatory phenotype seen in diabetes." (PMID 35954275, 2022). "Homeobox protein Hox-A3 (Hoxa3)-treated diabetes-derived macrophages exhibited HDAC inhibition, which quickens the wound healing process by inhibiting inflammatory factors." (PMID 34071497, 2021). "The importance of this effect of Hoxa3 is underscored by evidence that sustained levels of pro-inflammatory pathways in diabetes plays a major role in creating the chronic wound environment." (PMID 31626638, 2019). "Enforced Hoxa3 expression in hematopoietic progenitors was shown to promote their differentiation into Gr1+CD11b+ cells, a proangiogenic myeloid population, and rescue their diabetes-induced defects." (PMID 27342843, 2016). "Therefore, Hoxa3 can rescue both the defective phenotype and persistent immaturity; this is not surprising, as, in diabetes, the persistent inflammatory phenotype and immaturity of myeloid cells are intertwined processes." (PMID 35954275, 2022). "Hoxa3-treated mφs showed upregulation of maturation markers F4/80 and CD115 as well a master regulator of mφ development, Spi1/Pu.1, at both transcriptional and protein levels, thus supporting the hypothesis that Hoxa3 rescues diabetes-induced mφ maturation defects." (PMID 27342843, 2016).
colon cancer (4 papers, 2019 to 2023). "HOXA3 has been reported to participate in papillary thyroid cancer, lung adenocarcinoma, and colon cancer carcinogenesis and development." (PMID 33683826, 2021). "In tumors, HOXA3 is reported to promote human colon cancer formation by regulating the EGFR/Ras/Raf/MEK/ERK signaling pathway." (PMID 31615976, 2019). "A previous study demonstrated that HoxA3 promoted tumor growth and metastasis in colon cancer, but the biological function of HoxA3 in pancreatic cancer has never been addressed." (PMID 31137902, 2019).
lung carcinoma (4 papers, 2016 to 2024). "Similarly, hypermethylation of CpG sites in the HOXA3/HOXA4 region has been detected in lung cancer." (PMID 38311789, 2024). "Furthermore, HOXA3 is upregulated in liver cancer and GC, while it is downregulated in lung cancer." (PMID 38311789, 2024). "HOXA2, HOXA3, and HOXA5 have been recognized as target for DNA methylation in lung cancer, and they promoted carcinogenesis, but also acted as tumor-suppressor factors." (PMID 34262872, 2021). "However, the detailed functions and mechanisms of HOXA3 in lung cancer have not been studied." (PMID 31615976, 2019).
non-small cell lung carcinoma (4 papers, 2019 to 2024). A group of at least three distinct histological types of lung cancer, including non-small cell squamous cell carcinoma, adenocarcinoma, and large cell carcinoma. "The association of HOXA-AS2, HOXA11,HOTTIP, HOXA1, HOXA3 and HOXA4 expression with survival of non-small-cell lung cancer." (PMID 39121297, 2024). "HOXA3 is known to be an oncogene in non-small cell lung cancer and thyroid cancer." (PMID 37834206, 2023). "In non-small-cell lung carcinoma (NSCLC), lncRNA HOXA-AS3 interacted with HOXA3 and regulated EMT (epithelial-mesenchymal transition) and led to cisplatin resistance." (PMID 39019995, 2024).
papillary thyroid cancer (4 papers, 2021 to 2022). "HOXA-AS2 regulated the HOXA-AS2/miR-520a-3p/homeobox D8 and mitogen-activated protein kinase kinase kinase 2 axis in non-small lung cancer 46, and the miR-15a-5p/homeobox A3 (HOXA3) axis in papillary thyroid cancer." (PMID 33754013, 2021). "LncRNA HOXA-AS2 promotes tumorigenesis by regulating the miR-15a-5p/HOXA3 signaling in papillary thyroid cancer." (PMID 33526036, 2021).
lung adenocarcinoma (3 papers, 2021 to 2024). A carcinoma that arises from the lung and is characterized by the presence of malignant glandular epithelial cells. "We found that HOXA3 was low expressed in lung adenocarcinoma and had a protective effect on the prognosis of lung cancer patients; whereas HOXA11 and HOXA13 play oncogenic roles in lung adenocarcinoma 14-16." (PMID 35370463, 2022).
Alzheimer disease (2 papers, 2022 to 2024). A progressive, neurodegenerative disease characterized by loss of function and death of nerve cells in several areas of the brain leading to loss of cognitive function such as memory and language. "Differential hypermethylation in HOXA3 has been linked to neurodegeneration in late-onset Alzheimer's disease (AD)." (PMID 38311789, 2024).
glioblastoma (2 papers, 2023). The most malignant astrocytic tumor (WHO grade IV). "Transcription factor homeobox A3 (HOXA3) orchestrates the transcriptional activation of aerobic glycolysis, thereby inducing a profound enhancement in glioblastoma cell proliferation and tumour growth." (PMID 38052785, 2023).
hepatoblastoma (2 papers, 2021 to 2022). Hepatoblastoma (HB) is a malignant hepatic tumor and is the most common pediatric liver cancer. "The regulator of HOX‐AS2 is the chromatin remodeling factor ARID1B, suggesting an important role for the ARID1B/HOXA‐AS2/HOXA3 network in hepatoblastoma." (PMID 35592755, 2022). "HOXA‐AS2 prevented HOXA3 from degradation to participate in carcinogenesis in hepatoblastoma." (PMID 35592755, 2022).
leukemia (2 papers, 2019 to 2020). A malignant (clonal) hematologic disorder, involving hematopoietic stem cells and characterized by the presence of primitive or atypical myeloid or lymphoid cells in the bone marrow and the blood. "Compared to levels in Hoxa9/Meis1 leukemias, endogenous Hoxa9 and Hoxa10 were considerably elevated in SQSTM1-NUP214 leukemias, whereas the levels of Hoxa3, Hoxa5, Hoxa7, Hoxa11 and Meis1 were comparable in Hoxa9/Meis1 and SQSTM1-NUP214 leukemias." (PMID 32343715, 2020).
multiple myeloma (2 papers, 2021 to 2022). "Specifically, we found that healthy MSCs exposed to MM cells underwent gains (HOXA9, ACVR2A, EBF2) and losses (HOXA2, HOXA3, HOXC5) of DNA methylation in the direction of those observed for MSCs from myeloma patients." (PMID 33462210, 2021).
renal carcinoma (2 papers, 2019). A carcinoma arising from the epithelium of the renal parenchyma or the renal pelvis. "This FAK-YAP-HOXA3 pathway established in this study validates the regulatory roles of YAP and HOXA3 in renal cancer and how they were coordinated with the miR-10b to suppress the tumorigenesis of ccRCC." (PMID 30975094, 2019). "To further confirm the direct targeting of miR-10b on HOXA3, we analyzed the correlation between miR-10b and HOXA3 through the design of miR-10b mimics and inhibitors to monitor the expression of miR-10b in renal cancer cell." (PMID 30975094, 2019). "The results clearly showed that miR-10b regulates cell proliferation by targeting HOXA3 in renal cancer." (PMID 30975094, 2019).
thyroid (2 papers, 2015 to 2023). "HOXA3 deficient mice have severe defects not only in pharyngeal organ development, including thyroid hypoplasia and insufficiency, and parathyroid insufficiency, but also in endoderm and laryngeal cartilage as well as cranial nerves." (PMID 38259452, 2023).
acute promyelocytic leukemia (1 paper, 2017). An aggressive form of acute myeloid leukemia (AML), characterized by arrest of leukocyte differentiation at the promyelocyte stage, due to a specific chromosomal translocation t(15;17) in myeloid cells. "Recently, HOXA-AS2, a long non-coding RNA located between the HOXA3 and HOXA4 genes in the HOXA cluster, has been characterized as an oncogene in various cancers, including acute promyelocytic leukemia and gastric cancer." (PMID 28388535, 2017).
atherosclerosis (1 paper, 2024). A disease characterized by the build-up of fatty material and calcium deposition in the arterial wall resulting in partial or complete occlusion of the arterial lumen. "Homeobox Protein A3 (HOXA3) represents another transcription factor and is also involved both in thymogenesis and atherosclerosis." (PMID 39061983, 2024). "Thus, HOXA3 is characterized by pleiotropic effects, which may dampen the development of atherosclerosis both directly and through the modulation of thymus function." (PMID 39061983, 2024).
cervical cancer (1 paper, 2021). A primary or metastatic malignant neoplasm involving the cervix. "After normalization of the other clinical features (including TNM stage), only HOXA1 and HOXA3 expression was still associated with poor OS of cervical cancer, indicative of the fact that these two HOXA members could serve as independent predictive biomarkers of cervical cancer." (PMID 34606634, 2021). "However, among the remaining members of the HOXA family, HOXA3 also exhibited prognostic capability without differential expression in cervical cancer." (PMID 34606634, 2021).
idiopathic pulmonary fibrosis (1 paper, 2019). Idiopathic pulmonary fibrosis (IPF) is a nonneoplastic pulmonary disease that is characterized by the formation of scar tissue within the lungs in the absence of any known cause. "Furthermore, in a mouse model of idiopathic pulmonary fibrosis, HOXA3 was reported as an important modulator of EMT42." (PMID 31615976, 2019).
liver cancer (1 paper, 2021). An epithelial or non-epithelial malignant neoplasm that arises from the liver. "Moreover, the results of the present study showed that HOXA3 might interact with TRIM29, ENO1 and SFN, which was reportedly associated with the occurrence of liver cancer." (PMID 33683826, 2021).
meningioma (1 paper, 2013). A generally slow growing tumor attached to the dura mater. "Homeobox protein Hox-B3 (HOXB3), LIM domain only protein 3 (LMO3), Homeobox protein Hox-B6 (HOXB6), Homeobox protein Hox-A3 (HOXA3) and DNA-binding protein inhibitor ID-2 (ID2) showed higher under-expression in benignB with respect benignA meningiomas with a fold change lower than −3." (PMID 23840654, 2013).
pancreatic cancer (1 paper, 2019). "High expression of HoxA3, B8, and C5 is correlated with poor survival in pancreatic cancer, suggesting an oncogenic role of these members." (PMID 31137902, 2019). "Interestingly, the expression of HoxA3 and HoxB8 was continuously upregulated in pancreatic cancer cells with increased metastatic ability, while the expression of HoxA10, HoxA11, and HoxB13 was consistently reduced in these cells." (PMID 31137902, 2019). "As HoxA3 is significantly increased in KPA cells that exhibit aggressive behavior, we believe that HoxA3 acts as an oncogene in pancreatic cancer." (PMID 31137902, 2019). "As with HoxA3, no study has previously investigated the expression and clinical significance of HoxB8 in pancreatic cancer." (PMID 31137902, 2019).
pancreatic ductal adenocarcinoma (1 paper, 2022). An infiltrating adenocarcinoma that arises from the epithelial cells of the pancreas. "Several genes in the 500 kb vicinity of HOXA5 (i.e., HOXA3, HOXA9, HOXA7, HOXA1, EVX1) were also associated with high density lipoprotein (HDL) cholesterol efflux capacity, BMI, and pancreatic ductal adenocarcinoma." (PMID 35836279, 2022).
pressure ulcers (1 paper, 2023). "Because the wounds in this model were acute, and yet benefit was observed, the ideal application of HoxA3 may be as a home treatment for everyday wounds in the aged or elderly, or as an early intervention in pressure ulcers in a medical, long-term care, or assisted living facilities." (PMID 37337031, 2023).
sirenomelia (1 paper, 2012). Sirenomelia is a rare, genetic, developmental defect during embryogenesis disorder characterized by fusion of the lower limbs and associated with some degree of lower extremity reduction and persistent vitelline artery. "Indeed, loss of a single copy of Bmp4 and both copies of Bmp7 in Bmp4flox/+Bmp7flox/flox compound mutant mice (Hoxa3-Cre;Bmp4flox/+Bmp7flox/flox) resulted in hindlimb fusion as well as loss of the bladder and anal stenosis, essential diagnotic features of sirenomelia (n = 3)." (PMID 23028455, 2012).